MET (MET proto-oncogene, receptor tyrosine kinase)
Diseases named in the same sentence as MET in open-access papers (continued):
Sharing a sentence is not in itself a finding about the gene and the disease.
myeloma (continued). "Gene array analysis along with numerous other studies by us and others, identified the HGF/MET axis as a therapeutic target in myeloma." (PMID 24326130, 2013). "HGF/MET signaling is increasingly recognized as an important contributor to the pathogenesis of myeloma." (PMID 24326130, 2013). "Availability of a clinical candidate, its inhibitory potential for MET kinase, and the role of MET in myeloma cell survival provided compelling rationales for testing the effects of amuvatinib on myeloma cells." (PMID 24326130, 2013). "Amuvatinib readily inhibited MET phosphorylation in primary CD138+ cells from myeloma patients and in concordance, increased cell death." (PMID 24326130, 2013). "To elucidate in more detail the mechanism of action of amuvatinib in myeloma cells, we evaluated its effect on MET activity and downstream signaling in the myeloma cell line U266, which over-expresses HGF." (PMID 24326130, 2013). "To test this, we assessed the sensitivity of primary myeloma cells to the MET-kinase inhibitor, amuvatinib." (PMID 24326130, 2013). "Since amuvatinib is a small-molecule inhibitor that suppresses MET activity, we tested this agent as a proof-of-concept to therapeutically target MET in myeloma." (PMID 24326130, 2013). "Since the number of the primary CD138+ cells in eight patient samples were insufficient for performing a detailed investigation of HGF/MET signaling, we decided to further investigate the effects of amuvatinib in a myeloma cell line." (PMID 24326130, 2013). "In addition, the HGF/MET pathway is also considered an important therapeutic target in multiple myeloma." (PMID 40110197, 2025). "MiR-144 inhibited proliferation of multiple myeloma via suppressing c-MET." (PMID 31292167, 2019). "Together, these findings supported the hypothesis that suppressing HGF/c-MET signaling could be a rational strategy against relapsed/refractory myeloma, and we therefore performed a phase II clinical trial testing this possibility." (PMID 28337527, 2017). "Furthermore, reduction of MET using shRNAs or a ribozyme resulted in growth inhibition and apoptosis of myeloma cell lines." (PMID 28337527, 2017). "In myeloma, HGF-c-MET signaling was reported to induce myeloma cell proliferation and survival." (PMID 24716444, 2014). "This, together with the fact that myeloma cells frequently co-express c-MET, suggests the presence of an autocrine signaling loop, which could promote the survival and proliferation of myeloma cells." (PMID 24716444, 2014). "Taken together, these clinical findings strongly support our hypothesis that targeting the HGF/MET signaling pathway is a rational approach to myeloma therapy." (PMID 24326130, 2013). "Based on this background, we hypothesized that targeting the HGF/MET signaling pathway is a rational approach to myeloma therapy and that myeloma cells would be sensitive to amuvatinib." (PMID 24326130, 2013). "Our finding provides proof-of-principle that MET is important for the survival of myeloma cells and using a MET inhibitor such as amuvatinib may prove to be an effective strategy for treatment of MM." (PMID 24326130, 2013). "Together, these findings provide a rationale for targeting the HGF/MET signaling axis in myeloma." (PMID 24326130, 2013). "The effects of amuvatinib described here provide proof-of-concept that MET is important for the survival of myeloma cells and that reduction of its kinase activity may prove to be an effective targeted therapy." (PMID 24326130, 2013). "Moreover, amuvatinib treatment resulted in cell death in U266 myeloma cell line dependent on MET/HGF signaling, as measured by annexin V/PI staining and PARP cleavage." (PMID 24326130, 2013). "In addition, it has been recently shown that, in osteoblast-like cells, HGF/c-MET signaling could also be mediated by extracellular vesicles (EV) released by myeloma cells." (PMID 35582373, 2021). "Moreover, the c-MET inhibitors were found to block the response to HGF in a myeloma model." (PMID 26543328, 2015).
myeloma (continued). "Although some studies have shown that HGF/MET pathway might be implicated in B-cell neoplasms particularly diffuse large B-cell lymphoma (DLBL) and multiple myeloma (MM), it is still an unresolved issue for the impact of MET CNA in the survival of patients with these hematological malignancies." (PMID 23379953, 2013). "Syndecan 1 (CD138) on myeloma cells binds HGF and promotes c-MET signaling, while both potentiate interleukin-6-induced growth and migration, correlating with shorter survival." (PMID 28337527, 2017). "The c-MET receptor tyrosine kinase proto-oncogene regulates cell growth, survival, and migration, and c-MET signaling after engagement of its ligand, HGF, is a contributor to the pathogenesis of myeloma." (PMID 28337527, 2017). "Aberrant activation of HGF and/or its receptor c-MET has been described in solid tumors as well as in acute myeloid leukemia (AML), myeloma, and MPN." (PMID 26543328, 2015). "In the present study, we compared mRNA levels of MET and HGF in normal and primary myeloma plasma cells." (PMID 24326130, 2013). "The aim of this review is to summarize the key findings on the pathogenetic activity of HGF in multiple myeloma and further describe novel therapeutic approaches potentially helpful to overcome signals provided by the HGF/c-MET axis, putatively involved in drug resistance." (PMID 35582373, 2021). "The demonstration that decorin inhibited HGF-induced viability and migration of myeloma cell lines in vitro suggests that deregulation of the physiological crosstalk among decorin, HGF, and c-MET could have a role in disease pathogenesis." (PMID 35582373, 2021). "While levels of plasma HGF have been associated with myeloma, levels of HGF and MET mRNA in patient plasma cells have not been well evaluated nor correlated with disease status." (PMID 24326130, 2013). "In contrast, the drug did not induce apoptosis in another myeloma cell line (RPMI-8226/S) that is not dependent on the MET/HGF signaling axis due to lower levels of HGF (75% less) and MET (95% less)." (PMID 24326130, 2013). "In myeloma, a B-cell plasma malignancy, MET is neither mutated nor over-expressed, however, HGF is increased in plasma or serum obtained from myeloma patients and this was associated with poor prognosis." (PMID 24326130, 2013). "A synergy between MET inhibition (using MK8033, capmatinib, crizotinib, PHA-665752 or SU11274) and chemotherapy (carboplatin, paclitaxel, cisplatin, doxorubicin or bortezomib) has been reported in ovarian, gastric, osteosarcoma and MDR multiple myeloma cancer cell lines." (PMID 33526881, 2021). "If we accept these definitions, this suggests the possibility that the myeloma cells from our patients were not especially dependent on HGF/c-MET signaling and that selected patients with high HGF levels could have fared better." (PMID 28337527, 2017). "While expression of both HGF and MET transcripts has been shown to be present in myeloma cells and HGF mRNA has also been demonstrated to be expressed in bone marrow stromal cells the levels of HGF and MET mRNA in patient plasma cells have not been well evaluated nor correlated with disease status." (PMID 24326130, 2013).
gastric adenocarcinoma (31 papers, 2009 to 2025). "MET Proto-Oncogene, Receptor Tyrosine Kinase (MET) in the gastric adenocarcinoma cell lines Hs 746T and MKN-45." (PMID 41421967, 2025). "Cellular binding assays confirmed the specificity of radiotracer binding toward human hepatocyte growth-factor receptor (c-MET) expression on the surface of MNK-45 gastric adenocarcinoma cells." (PMID 40123688, 2025). "Molecular targets, such as epidermal growth factor receptor (EGFR), mammalian target of rapamycin (mTOR), and c-MET, have shown significant involvement in the aggressiveness of gastric adenocarcinomas." (PMID 39033209, 2024). "Our study addresses this gap by screening pairwise pharmacological interactions of EGFR, mTOR, and c-MET inhibitors with chemotherapeutics from five distinct groups in gastric adenocarcinoma cells, rigorously inspecting the kinetics of cell death." (PMID 39033209, 2024). "These researchers showed that c-MET expression was significantly reduced in the human gastric adenocarcinoma cell line, SGC7901, when the cells were treated with siRNA-c-MET-loaded exosomes using qPCR and Western blotting." (PMID 39355533, 2024). "Recently, MET amp has also been described as oncogenic, and studies using fluorescence in situ hybridization (FISH) have found MET amp in up to ~5% of patients with NSCLC or gastric adenocarcinoma." (PMID 34677235, 2021). "A total of 816 gastric adenocarcinoma patients were included and MET and HER2 immunohistochemical (IHC) staining were performed." (PMID 28052014, 2017). "The model of choice was the GTL-16 cell line, derived from a poorly differentiated gastric adenocarcinoma, in which the MET gene locus is amplified, leading to overexpression of constitutively active MET protein." (PMID 25473895, 2015). "Inhibition of MET activity by EMD1214063 induced autophagy in gastric adenocarcinoma cell lines and inhibition of autophagy in combination with MET inhibition led to significant cell death." (PMID 25110867, 2014). "Here, we report that N- acetylgalactosaminyltransferase 2 (GALNT2), an enzyme that mediates the initial step of mucin type-O glycosylation, suppresses malignant phenotypes in gastric adenocarcinoma (GCA) by modifying MET (Hepatocyte growth factor receptor) activity." (PMID 26848976, 2016). "Finally, a recent report in patients with gastric adenocarcinoma has suggested that MET staining pattern can predict MET gene amplification." (PMID 26041880, 2015). "Therefore, the relation of the expression of c-MET, e2f-1 and Ki-67 with the profiles of clinicopathological parameters and prognosis in the patients with gastric adenocarcinoma (GC) would be investigated in this study of ours." (PMID 24393368, 2014). "In a cohort of 950 patients with treatment-naïve gastric adenocarcinoma, 63.1% of tumors expressed at least one receptor tyrosine kinase (HER2, EGFR, MET, FGFR2), while 22.7% of these simultaneously expressed multiple biomarkers." (PMID 41303727, 2025). "This study was conducted to investigate the expression of MET in Chinese gastric adenocarcinoma cohort, the correlation between MET overexpression and clinical pathological features, HER2 expression and MET gene amplification." (PMID 28052014, 2017). "Tissue microarray analyzed that HER2, EGFR, MET and FGFR2 predominances were respectively observed in 10.1, 13.9, 16.1 and 22.9% of the gastric adenocarcinomas." (PMID 27738318, 2016). "In gastric adenocarcinoma, downregulation of GALNT2 increased the cell proliferation, migration, invasion and tumor metastasis by increasing the phosphorylation of hepatocyte growth factor receptor (MET: a receptor tyrosine kinase like IGF-l) and decreasing the expression of the Tn antigen on MET." (PMID 27322213, 2016). "For instance, the prognostic significance of HER2 and MET protein expression level, FGFR2 gene amplification, and downstream mediators pS6 and pERK was evaluated for their potential utility as biomarkers in patients with gastric adenocarcinoma." (PMID 28536405, 2015).
gastric adenocarcinoma (continued). "ERBB2 amplification for anti-ERBB2 inhibitor treatment in breast and gastric adenocarcinomas, EGFR amplification for anti-EGFR inhibitors, MET amplification for MET tyrosine kinase inhibitors, and FGFR2 amplification for FGFR2 phosphorylation inhibitors have been reported as predictive markers." (PMID 23936009, 2013). "UWG02CTC also showed higher expression than UWG01CTC of targetable pathways including EGFR, FGFR2, HER-2 (ERBB2), and MET, as well as key genes in the JAK/STAT pathway, genes which overexpression are frequently reported in gastric adenocarcinomas but not gastrointestinal neuroendocrine cancers." (PMID 31953491, 2020).
brain tumor (30 papers, 2008 to 2026). "For the brain tumor cohort, an oncoprint plot of the top 25 mutated genes was created for patients with MET mutations." (PMID 41521799, 2026). "This research provides a better understanding of MET mutation characteristics in lung and brain tumors, offering further insights into potential treatments for patients with different MET mutations in these cancers." (PMID 41521799, 2026). "Detailed pharmacokinetic analyses are critical to identify the optimal MET inhibitor for brain tumor therapy." (PMID 38849845, 2024). "SGX523 treatment inhibits c-MET-dependent brain tumor cell proliferation and G1/S cell cycle progression, and SGX523 also inhibits brain tumor cell migration and invasion." (PMID 37318594, 2023). "PTPRZ1 also forms a fusion with the nearby oncogene MET in some brain tumors that have an overexpression of the fused MET41." (PMID 35338126, 2022). "Studies of HGF/c-MET distribution in human primary brain tumors showed that expression was not limited to glial cancer cells, but was also found in supporting tumor microvasculature." (PMID 36034555, 2022). "Brain tumours secrete scatter factor (SF)/hepatocyte growth factor (HGF), the activating ligand for HGFR/MET, which has been associated with poor prognosis for GBM patients." (PMID 31616641, 2019). "In this study, we have further discovered that treatment with crizotinib inhibited MET phosphorylation in brain tumors produced by NUGC4 cells, as determined by immunohistochemistry." (PMID 29125233, 2017). "Scatter factor (SF)/hepatocyte growth factor (HGF) is the activating ligand for HGFR/c-MET that have been shown to be secreted by brain tumor cells." (PMID 29263927, 2017). "Brain Tumor Project reported a recurrent drug-targetable MET fusion gene in pediatric GBMs." (PMID 34055785, 2021). "The results showed that miR-34a suppressed brain tumor growth by targeting MET and Notch." (PMID 22829753, 2012). "In order to specifically target brain tumors, CPP and an apolipoprotein E peptide (ApoEP) were attached to the external surface of GFP-Qβ VLPs-RNAic-MET (dP@gVLP/RNAic-MET)." (PMID 36714624, 2022). "Notably, important oncogenes involved in brain tumor development are located on these chromosomes, such as PDGFR1 and FGFR2 on chromosome 4, EGFR and MET on chromosome 7, and CDK4 and MDM2 on chromosome 12." (PMID 41323387, 2025). "So far, MET inhibition-mediated radiosensitization has not been explored in the context of pediatric brain tumors." (PMID 38849845, 2024). "Most MET404 KI mice had developed brain tumours at 20 weeks (displayed central nervous system symptoms including paralysis, seizure and/or ataxia), and the tumour phenotypes were very similar to those of GBM, with highly activated MET signalling." (PMID 37491377, 2023).
cholangiocarcinoma (30 papers, 2010 to 2025). A carcinoma that arises from the intrahepatic biliary tree (intrahepatic cholangiocarcinoma) or from the junction, or adjacent to the junction, of the right and left hepatic ducts (hilar cholangiocarcinoma). "For example, all four of the mutations were detected in the ctDNA of a patient with an NTRK fusion‐positive, MET amplified cholangiocarcinoma that progressed on the combination of selitrectinib (TRKi) and crizotinib (METi)." (PMID 40437874, 2025). "For some cancers, including cholangiocarcinoma, gastric or skin cancer, a clear correlation between c-MET expression level and a poor prognosis has been demonstrated." (PMID 23251249, 2013). "Specifically, this patient had stage IV PLEKHA6‐NTRK1, MET amplified (fold change: 12.3) cholangiocarcinoma which initially responded and then became resistant to the combination therapy with the TRK inhibitor selitrectinib and the type I MET inhibitor crizotinib." (PMID 40437874, 2025). "Other targets, such as anti-angiogenesis, EGFR amp, WNT/a-catenin, Hedgehog, and HGF/c-MET, have been reported in cholangiocarcinoma, but most of these pathways can be found in most tumour types, and multiple previous clinical trials in cholangiocarcinoma have shown limited effectiveness." (PMID 36612035, 2022). "RBPMS, an RNA-binding protein, and MET, a proto-oncogene receptor tyrosine kinase, have been identified as fusion partners in a variety of cancers with other genes and as gene fusion partners in a patient with cholangiocarcinoma." (PMID 34863095, 2021). "Additionally, treatment of HGF-stimulated cholangiocarcinoma cells with MET siRNA led to the disappearance of actin-rich protrusions." (PMID 31649529, 2019). "A recent study reported a patient with cholangiocarcinoma harboring a CAPZA2–MET fusion along with MET amplification, who dramatically responded to capmatinib, a specific MET TK inhibitor." (PMID 38363490, 2024). "A recent phase II trial in bile duct cancer with cabozantinib, a multi-kinase inhibitor targeting VEGFR2, MET and AXL, supports targeting receptor tyrosine kinases such as AXL as possible therapeutic targets to treat cholangiocarcinoma." (PMID 36980768, 2023). "The applicability of GenoCTC to different cell surface biomarkers was also validated in a cholangiocarcinoma patient using anti-EPCAM, anti-vimentin, or anti-tyrosine protein kinase MET (c-MET) antibodies." (PMID 32486306, 2020). "The effect of tivantinib on cell viability was assessed in a wide panel of cell lines exhibiting different levels of c-MET expression including 4 HCC cell lines, one cholangiocellular carcinoma cell line, and three additional cancer cell lines from tumors of gastrointestinal origin." (PMID 26259250, 2015). "This case may indicate that c-MET inhibition is a reasonable consideration in patients with MET-amplified cholangiocarcinoma in whom cytotoxic therapy is no longer an option." (PMID 35129063, 2022). "Here, we enumerated and analyzed CTCs from a cholangiocarcinoma patient using the epithelial marker EPCAM and the non-epithelial markers vimentin and MET." (PMID 32486306, 2020). "EGF, HGF/MET, VEGF, KRAS/MAPK, and IL-6/STAT pathways have been found to be deregulated in cholangiocarcinoma, but no effective therapies targeting these pathways have been developed." (PMID 26475437, 2015).